MSH6 (mutS homolog 6)
Diseases named in the same sentence as MSH6 in open-access papers (continued):
Sharing a sentence is not in itself a finding about the gene and the disease.
Lynch syndrome (continued). "For example, if a patient tests positive for a pathogenic mutation in MSH6 but does not have a personal or family history suggestive of classic Lynch Syndrome, delay of initial colonoscopy to age 25–30 or less frequent colonoscopies could be considered." (PMID 33541411, 2021). "The co-occurrence of the truncating mutation with p.R976C in MSH6 in addition to the loss of MSH6 protein expression (factored in with family history, in silico modeling, etc.)provided evidence to upgrade this VUS to a likely pathogenic variant and diagnosis was changed to Lynch syndrome." (PMID 29755653, 2018). "However, we find unlikely its association with the PrCa in this patient, as no loss of MSH6 expression was observed in the tumor (contrarily to what we observed in the colon carcinomas of our Lynch syndrome families)." (PMID 29659569, 2018). "In the MSI pathway observed in Lynch syndrome, CRC formation is driven by the acquisition of mutations at the level of the coding sequences of genes, such as growth factor receptors (TGFBR2 and IGF2R), genes involved in apoptosis (BAX) and DNA repair (MSH3 and MSH6)." (PMID 29652830, 2018).
Lynch syndrome (continued). "We report 15 novel MSH6 mutations and 1 novel PMS2 mutations in Lynch syndrome families not listed in the Mismatch Repair Genes Variant Database (Memorial University of Newfoundland), the InSIGHT database as a Lynch syndrome mutation or the Leiden Open Variation Database (LOVD)." (PMID 20487569, 2010). "Five cases exhibited combinations of HBOC and endocrine or Lynch syndrome genes (e.g., SDHAF2, SDHA, MSH6)." (PMID 40943312, 2025). "The genome panel test revealed mutations in the following two DNA mismatch repair (MMR) genes observed in Lynch syndrome: MLH1 and MSH6." (PMID 37086325, 2023).
Lynch syndrome (continued). "Moreover, several studies have reported that Lynch syndrome with germline mutations in MSH6 or PMS2 might not necessarily show MSI-H30,31." (PMID 34625576, 2021). "In MSI testing, colorectal cancer from MSH6 associated Lynch syndrome may not demonstrate MSI-H." (PMID 34185173, 2021). "There is good reported concordance between MSI and immunohistochemistry testing for Lynch syndrome tumour identification, but more recent data suggest that MSI testing is less accurate in endometrial cancer – particularly at identifying MSH6 carriers." (PMID 33679238, 2021).
Lynch syndrome (continued). "MSH6 takes part in MMR and it is directly involved in cancer onset due to its direct role in Lynch syndrome." (PMID 28206966, 2017). "One of the major objections levelled against the original NCI panel concerned the screening of tumours with defective MSH6, one of the four major MMR genes responsible for Lynch syndrome." (PMID 21081928, 2010).
Lynch syndrome (continued). "Since MSH6-Lynch syndrome is less likely to present with CRC, screening of UTUC diagnoses may be particularly valuable for this Lynch syndrome subtype." (PMID 41138669, 2025). "In addition, the presence of two biallelic MSH6 mutations may suggest the possibility that they may not all be somatic, but one (or both) may have been inherited, making patient 19 a possible case of Lynch syndrome." (PMID 37175518, 2023). "We found that IHC with a two-antibody (MSH6 and PMS2) panel would detect all 16 (100%) Lynch syndrome cases in the PETALS study, and on the basis of the assumption that it would halve the cost of IHC testing, it would also result in cost saving, costing £1200 per Lynch syndrome case identified." (PMID 32492863, 2020).